DPP4 (dipeptidyl peptidase 4)
Diseases named in the same sentence as DPP4 in open-access papers (continued):
Sharing a sentence is not in itself a finding about the gene and the disease.
HIV-1 infection (3 papers, 2010 to 2020). The type species of lentivirus and the etiologic agent of acquired immunodeficiency syndrome (AIDS). "Recent findings showed that lower levels of soluble DPP4 were associated with a poorer prognosis in HIV-1 infection." (PMID 32946499, 2020). "Possibly, low frequencies of DPP4 T cells in HIV-1 infection are be due to the early loss of Th17 T cells in HIV infection." (PMID 32946499, 2020). "Our observations illustrate that DPP4 is a component of T cell biology involved in sex differences in chronic HIV-1 infection." (PMID 32946499, 2020). "Given the decrease of CD4+DPP4+ T cells in progressive HIV-1 infection, we assessed the correlation of DPP4+CD4+ T cells with markers of disease progression." (PMID 32946499, 2020). "Possibly this is due to the strong reduction of CD8+DPP4+ T cell percentages in HIV-1 infection, which was more pronounced for CD8+ T cells than for CD4+ T cells." (PMID 32946499, 2020). "Sex differences in DPP4 expression abrogated in progressive HIV-1 infection." (PMID 32946499, 2020). "Similarly, Morimoto and co-workers have demonstrated that Jurkat T cell line expressing very high levels of DPP4 activity were resistant to HIV-1 infection." (PMID 22291902, 2012). "Taken together, these results suggest that high CD4+DPP4+ T cell frequencies correlate with more favorable prognostic surrogate markers of HIV-1 infection in women but not in men." (PMID 32946499, 2020).
hypertensive nephropathy (3 papers, 2019 to 2025). Kidney damage that results from chronically elevated blood pressure; complications include glomerular damage resulting in proteinuria and hematuria. "Our data on the renal GLP-1R expression in HS animals and the increase in urine sodium concentration following DPP4 inhibition indicate a role of this system also in the pathobiology of hypertensive chronic kidney disease." (PMID 30774748, 2019).
hypoalphalipoproteinemia (3 papers, 2021 to 2025). A metabolic disorder characterized by deficiency of high density (alpha) lipoprotein in the blood. "We aimed to assess the association of DPP4 gene polymorphisms with hypoalphalipoproteinemia and DPP4 serum levels, in a cohort of Mexican individuals." (PMID 34178021, 2021). "Considering that this is the first study to report the association of DPP4 polymorphisms with the presence of hypoalphalipoproteinemia, studies in other populations are necessary to confirm our results." (PMID 34178021, 2021). "Our results showed that non-hypoalphalipoproteinemia subjects have significantly higher DPP4 concentrations." (PMID 34178021, 2021). "DPP4 isoforms with altered activity could be involved in the development of hypoalphalipoproteinemia." (PMID 34178021, 2021). "Five DPP4 polymorphisms (rs12617336, rs12617656, rs1558957, and rs3788979, and rs17574) were genotyped in 748 participants with and 745 without hypoalphalipoproteinemia." (PMID 34178021, 2021). "The DPP4 serum concentration and its association with rs17574 genotypes were evaluated separately in individuals with and without hypoalphalipoproteinemia." (PMID 34178021, 2021). "On the other hand, individuals without hypoalphalipoproteinemia presented higher DPP4 levels when compared to individuals with hypoalphalipoproteinemia." (PMID 34178021, 2021).
interstitial lung disease (3 papers, 2020 to 2024). A diverse group of lung diseases that affect the lung parenchyma. "Additionally, metformin (ROR 0.43, 95%CI 0.33-0.57; IC -1.09, 95%CI -1.49 to -0.69), sulfonylureas (ROR 0.64, 95%CI 0.48-0.86; IC -0.59, 95%CI -1.00 to -0.17), and DPP-4 inhibitors (ROR 0.47, 95%CI 0.27-0.81; IC -0.99, 95%CI -1.76 to -0.22) were inversely associated with interstitial lung disease." (PMID 32132864, 2020).
ischemic cardiomyopathy (3 papers, 2018 to 2024). Ischemic cardiomyopathy is a cardiomyopathy in which a weakness in the muscle of the heart due to inadequate oxygen delivery to the myocardium with coronary artery disease being the most common cause. "Based on these findings, we compared the intra-operative DPP4 activity profile in patients with preserved vs. reduced left ventricular (LV) function, the latter closely related to ischemic cardiomyopathy." (PMID 30087386, 2018).
lupus nephritis (3 papers, 2024 to 2026). Glomerulonephritis in the context of systemic lupus erythematosus. "Combined DPP-4 and CXCL12/CXCR4 axis inhibition synergistically enhanced podocyte protection and attenuated renal inflammation, fibrosis, and oxidative stress in lupus nephritis." (PMID 41601976, 2026).
metastasis (3 papers, 2021 to 2022). The spread or migration of cancer cells from one part of the body (where they first appeared) to another. "Interestingly, our analysis revealed that the mRNA expressions levels of DPP4/CTNNB1/MET were more elevated in stage IV of THCA cancer, and were significantly elevated in metastasis tumor compared with the primary tumor." (PMID 35205190, 2022).
myocarditis (3 papers, 2015 to 2026). Myocarditis is a condition that is characterized by inflammation of the heart muscle (myocardium). "Western blotting and immunostaining showed an elevated cardiac DPP4 expression in mice with Coxsackievirus B3 (CVB3) myocarditis." (PMID 41984505, 2026). "DPP-4 inhibition was reported to suppress transforming growth factor β (TGF-β) and α-smooth muscle actin (α-SMA) expression, and treatment with a DPP-4 inhibitor reduced fibrosis in a model of myocarditis in mice." (PMID 28118775, 2017). "As various factors, such as virus infection and autoimmunity, are related to myocarditis, the effects of DPP-4 inhibitors should also be elucidated through the use of a viral myocarditis model." (PMID 25768281, 2015). "The DPP-4 inhibitors effect on cardiovascular disease led us to hypothesize that it also has beneficial effects on myocarditis." (PMID 25768281, 2015). "Thus, the agents present in DPP-4 inhibitors may be useful to treat and/or prevent clinical myocarditis." (PMID 25768281, 2015). "We developed a novel PET probe, 68Ga-DOTA-linagliptin (abbreviated as 68Ga-linagliptin), which targets dipeptidyl peptidase-4 (DPP4), to assess its potential in detecting myocarditis." (PMID 41984505, 2026). "However, the role of a DPP-4 inhibitor on myocarditis has not been investigated." (PMID 25768281, 2015).
prostate tumor (3 papers, 2009 to 2022). "Oncomine data analysis comparing transcript expression of DPP4, TSPAN8, and NES between prostate tumor tissues and normal tissues revealed inconsistent upregulation of these genes in the different datasets." (PMID 30100995, 2018).
Pruritus (3 papers, 2023 to 2024). Pruritus is an itch or a sensation that makes a person want to scratch. "Pruritus is the most common cutaneous ADR of DPP-4 inhibitors reported in RCTs, with alogliptin and teneligliptin being the most frequently implicated drugs." (PMID 38523307, 2024). "Especially in patients with severe generalized pruritus who do not respond to standard antipruritic treatments, the use of DPP-4 inhibitors, one class of oral antidiabetic agents, should be questioned and all medications used by the patient should be reviewed." (PMID 38813039, 2023). "Especially in patients with severe generalized pruritus who do not respond to standard antipruritic treatments, the use of DPP-4 inhibitors, a class of oral antidiabetic agents, should be questioned and all medications being used by the patient should be reviewed." (PMID 38813039, 2023).
rheumatic disease (3 papers, 2022 to 2025). "Increased DPP4 activity is associated with decreased severity of rheumatic disease due to the dual role of CD26 involving cytokine inhibition and inducing cellular immunity." (PMID 36468400, 2022).
squamous cell carcinoma (3 papers, 2020 to 2025). A carcinoma arising from squamous epithelial cells. "In squamous cell carcinoma cases, DPP4 was weakly expressed in both normal and tumor tissues, whereas PSA was highly expressed in tumor tissues, but not in normal tissues (n = 3)." (PMID 35650221, 2022). "Both adenocarcinoma and squamous cell carcinoma showed positive immunostaining for DPP4." (PMID 35650221, 2022).
thyroid nodule (3 papers, 2006 to 2022). A small circumscribed mass in the THYROID GLAND that can be of neoplastic growth or non-neoplastic abnormality. "Further analysis showed a clear trend that, among the seven types of thyroid nodules, DPP4 expressed higher in malignant nodules than in benign nodules, especially the most elevated one in MTC nodules, although the difference was not significant (p > 0.05)." (PMID 36467461, 2022). "In the present series, we compared the performance of TPO, DPP4, and HBME-1 on FNA smears obtained from 200 thyroid nodules before or after surgical resection." (PMID 18212751, 2008).
ulcer (3 papers, 2012 to 2025). "Collectively, the findings of this study, in conjunction with those of previous studies, support that DPP‐4 inhibitors can effectively promote ulcer healing." (PMID 40948240, 2025). "Although elucidation of the pathophysiologic importance of these aspects awaits further confirmations, the present study evidences an additional aspect of how DPP-4 inhibition might contribute to improved ulcer outcome." (PMID 23197976, 2012).
urticaria (3 papers, 2012 to 2024). A vascular reaction of the skin characterized by erythema and wheal formation due to localized increase of vascular permeability. "One adverse drug reaction (urticaria) was observed in the GEM group, which is a well-recognized AE associated with DPP4 inhibitors." (PMID 38223523, 2024).
viral hepatitis (3 papers, 2016 to 2023). An acute or chronic inflammation of the liver parenchyma caused by viruses. "Supporting increased fibrosis, blinded meta-analysis of histological data in viral hepatitis (METAVIR) histopathological scoring of liver samples revealed a shift of 33% in Dpp4–/– mice to level 4 relative to littermate controls, while no Dpp4hep–/– mice were scored in this range." (PMID 36472923, 2023).
Airway obstruction (2 papers, 2013 to 2023). Obstruction of conducting airways of the lung. "PA positively correlated with DPP4 activity, but negatively correlated with forced expiratory volume in 1 s (FEV1) % predicted, an indicator of airway obstruction." (PMID 37287831, 2023).
allergic asthma (2 papers, 2016 to 2019). A asthma with a basis in a pathological type I hypersensitivity reaction. "Van der Velden investigated DPP4 expression in allergic asthma and normal controls, and showed that DPP4 was mainly expressed in blood vessels and mucosal glands and T cells." (PMID 26975422, 2016).
aortic valve disease (2 papers, 2021 to 2025). "Moreover, DPP4 induced valvular calcification and promoted calcific aortic valve disease progression by inhibiting autocrine insulin-like growth factor-1 (IGF-1) signaling." (PMID 34497344, 2021).
bacteremia (2 papers, 2021 to 2024). "Hence, bacterial DPP-4 could reduce the host’s incretin concentrations when these microorganisms enter the circulation through routine activities (recurrent bacteremia)." (PMID 38337597, 2024).
bipolar disorder (2 papers, 2021 to 2025). A disorder of the brain that causes unusual shifts in mood, energy, activity levels and the ability to carry out day-to-day tasks. "This study investigates whether SGLT-2i use is associated with a lower risk of suicide-related events compared to dipeptidyl peptidase-4 inhibitors (DPP-4i) in individuals with bipolar disorder and T2DM." (PMID 40567368, 2025).
bone fracture (2 papers, 2012 to 2015). "So far it has been shown that sitagliptin improves fatty liver, that GIP contributes to bone metabolism, and, from a meta-analysis, that the risk of bone fracture is significantly reduced in patients treated with DPP-4 inhibitors." (PMID 23024732, 2012).
cholelithiasis (2 papers, 2016 to 2022). The presence of crystallized deposits forming in the gallbladder or biliary tree, primarily composed of cholesterol, bilirubin, and bile. "With regard to risks of cholelithiasis, no significant heterogeneity was found in each subgroup analysis according to patient age, trial duration, or DPP4 inhibitor agents." (PMID 36271423, 2022).
Chronic Lymphocytic Leukemia (2 papers, 2022 to 2023). "Clinical trials of the combination of the DPP4 nonselective inhibitor Val-boro-Pro and rituximab in the treatment of primary drug-resistant and indolent non-Hodgkin’s lymphoma and chronic lymphocytic leukemia (CLL) have been conducted in the early years." (PMID 36172198, 2022).
delirium (2 papers, 2022 to 2025). A disorder characterized by confusion; inattentiveness; disorientation; illusions; hallucinations; agitation; and in some instances autonomic nervous system overactivity. "DPP‐4 inhibitors specifically, are likely linked to hypoglycaemic episodes, which is a potential trigger for delirium." (PMID 40843954, 2025). "It is unclear whether DPP-4 inhibitors have an impact on hospitalization, falls, fractures and delirium compared with no add-on treatment because either no study assessed these predefined outcomes or the quality of evidence was very low." (PMID 35111291, 2022).
dermatitis (2 papers, 2024). An inflammatory process affecting the skin. "In a dermatitis model induced by 1-chloro-2,4-dinitrochlorobenzene, representing Th1-like inflammation, the ears of CD26/DPP4-deficient rats exhibited more pronounced thickening compared with those of wild-type rats." (PMID 38263019, 2024).
edema (2 papers, 2023 to 2025). An abnormal accumulation of fluid beneath the skin, or in one or more cavities of the body. "While AT1/NEP inhibitors, DPP-4 inhibitors, HMGR inhibitors, MR antagonists, or PPAR-gamma agonists were all found to significantly normalize pulmonary edema/lung congestion, this parameter was assessed in only 49/194 (25%) papers." (PMID 37895920, 2023).
epilepsy (2 papers, 2021 to 2025). A brain disorder characterized by episodes of abnormally increased neuronal discharge resulting in transient episodes of sensory or motor neurological dysfunction, or psychic dysfunction. "Analysis of public RNA-sequencing data revealed predisposing factors (such as dipeptidyl peptidase IV; DPP4) for epilepsy related to DAM conversion." (PMID 33975617, 2021). "Here we made a comprehensive analysis of the Gene Expression Omnibus (GEO) database and found that dipeptidyl peptidase IV (DPP4) was associated with DAM phenotypic transformation in epilepsy." (PMID 33975617, 2021). "Thus, this study aims to determine whether DPP4 influence DAM phenotypic transformation in epilepsy and try to explore the potential underlying mechanisms." (PMID 33975617, 2021). "The present results highlight that the DPP4 inhibitor sitagliptin can attenuate epilepsy and promote DAM phenotypic transformation." (PMID 33975617, 2021). "Using GEO database, we found that DPP4 and Cp overexpression was associated with the dysregulation of TREM2 and epilepsy." (PMID 33975617, 2021). "The treatment of sitagliptin (a DPP4 inhibitor) attenuated KA-induced epilepsy and promoted the expression of DAM markers (Itgax and Axl) in both mouse epilepsy model in vivo and microglial inflammatory model in vitro." (PMID 33975617, 2021). "To observe the changes in epilepsy treated with DPP4 inhibitor sitagliptin, we evaluated epileptic seizures by EEG recordings." (PMID 33975617, 2021). "Similarly, DPP-4 inhibitors have also shown promise in managing Huntington disease and epilepsy owing to their significant potentiation of GABAergic neurotransmission, likely via their indirect GLP-1 receptor agonism." (PMID 39904872, 2025). "In a KA-induced epilepsy model, we found that sitagliptin attenuated KA-induced epilepsy and increased the expression of ITGAX in microglia, which suggested that DPP4 inhibiting could promote DAM conversion." (PMID 33975617, 2021). "Our results demonstrated that DPP4 participated in DAM conversion and epilepsy." (PMID 33975617, 2021). "Thus, we propose DPP4 may act as an attractive direction for DAM research and a potential therapeutic target for epilepsy." (PMID 33975617, 2021).
familial partial lipodystrophy type 2 (2 papers, 2017 to 2019). "The aim of this study was to evaluate DPP4 levels in patients with familial partial lipodystrophy type 2 (FPLD2) and correlate it with body fat distribution." (PMID 28450900, 2017).
Fanconi anemia complementation group D2 (2 papers, 2022 to 2024). Fanconi anemia caused by mutations of the FANCD2 gene.
gastric neoplasm (2 papers, 2020 to 2026). A benign or malignant neoplasm involving the stomach. "Whether the risk of gastric neoplasm is modified by newer glucose-lowering therapies-dipeptidyl peptidase-4 inhibitors (DPP4is), glucagon-like peptide-1 receptor agonists (GLP1RAs), and sodium-glucose cotransporter 2 inhibitors (SGLT2is)-remains uncertain." (PMID 41898482, 2026).
Hashimoto thyroiditis (2 papers, 2023 to 2024). An autoimmune disorder caused by the production of autoantibodies against thyroid tissue. "A recent study found that patients with Hashimoto’s thyroiditis had decreased serum concentration and activity of DPP4." (PMID 37350750, 2023).
herpes zoster (2 papers, 2018 to 2022). A common dermal and neurologic disorder caused by reactivation of the varicella-zoster virus that has remained dormant within dorsal root ganglia, often for decades, after the patient's initial exposure to the virus in the form of varicella (chickenpox). "The association between DPP-4 inhibitors and increased incidence of herpes zoster might be due to the inhibition of CD26 by these agents." (PMID 29520743, 2018). "In addition, treatment with thiazolidinediones, alpha-glucosidase inhibitors, dipeptidyl peptidase-4 inhibitors (DPP-4) and insulin appears to increase the risk of herpes zoster, whereas metformin and sulphonylureas do not appear to affect this risk." (PMID 29520743, 2018).
hip fracture (2 papers, 2020 to 2025). Traumatic or pathological injury to the hip in which the continuity of either the femoral head, femoral neck, intertrochanteric or subtrochanteric regions is broken. "Furthermore, our data for the first time indicate that plasma DPP4 activities were also positively related to the 10-year probability of major osteoporotic fracture and hip fracture estimated by modified FRAX in newly diagnosed type 2 diabetic patients." (PMID 33312197, 2020).
hyperandrogenism (2 papers, 2024 to 2025). Excessive secretion of androgens from the adrenal glands or gonads. "Before exploring the mechanisms through which DPP4 influences endometrial receptivity, we constructed a hyperandrogenism-induced cell model to clarify the association between ferroptosis and endometrial receptivity in PCOS." (PMID 41437396, 2025). "Based on these observations, our findings demonstrate that DPP4 inhibition effectively rescues the impaired decidualization capacity and restores functional endometrial receptivity in a hyperandrogenism-induced PCOS model." (PMID 41437396, 2025). "This suggests that DPP4 may link hyperandrogenism to ferroptosis in PCOS." (PMID 41437396, 2025).
ischemia reperfusion injury (2 papers, 2020 to 2021). Adverse functional, metabolic, or structural changes in ischemic tissues resulting from the restoration of blood flow to the tissue (reperfusion), including swelling; hemorrhage; necrosis; and damage from free radicals. "In the present study, we took advantage of an ex vivo system to compare the cardiac effects of different DPP-4 inhibitors, observing that linagliptin consistently improved the recovery of contractile function after ischemia reperfusion injury." (PMID 32796688, 2020). "In addition to the glucose-lowering effects of DPP-4 inhibitors, tissue-protective effects of DPP-4 inhibition have been demonstrated in ischemia-reperfusion injury, DKD, and CKD." (PMID 34697593, 2021).